DPAGT1 (dolichyl-phosphate N-acetylglucosaminephosphotransferase 1)
Diseases named in the same sentence as DPAGT1 in open-access papers (continued):
Sharing a sentence is not in itself a finding about the gene and the disease.
tumor (10 papers, 2014 to 2025). "MC-38 tumor-bearing mice, which were injected with the mutated peptide vaccine (Adpgk, Reps1, and Dpagt1), showed the suppression of tumor growth." (PMID 30662919, 2018). "Inhibition of N-glycosylation with tunicamycin disrupts RTK signaling in tumor cells and enhances susceptibility of lung cancer cells to a therapeutic agent, erlotinib, emphasizing the importance of DPAGT1/N-glycosylation in RTK signaling in cancer." (PMID 24742667, 2014). "In addition to GANAB, there are numerous N-glycosylation-associated markers that were reported being strongly associated with tumor progression such as DPAGT1." (PMID 35879690, 2022). "They interfere with N-glycan biosynthesis, a process that becomes particularly critical in cancer cells where DPAGT1 is overexpressed to sustain tumor growth and progression." (PMID 41157066, 2025). "Genetic deletion of DPAGT1 reduces the glycosylation of E-cadherin and downregulates the canonical Wnt signaling pathway, inhibiting tumor cell invasion and metastasis." (PMID 38534381, 2024). "Significantly, high DPAGT1 expression was strongly correlated with tumor relapse, patient death, and several clinicopathological characteristics, including advanced stages and higher Ki67 expression." (PMID 37463446, 2023). "The overexpression of ATP5J2 is correlated with enhanced cell migration and decreased 5-FU sensitivity in CRC and the overexpression of the DPAGT1 inhibits E-cadherin’s adhesive function and disrupts tumor cell cohesion." (PMID 33799486, 2021). "DPAGT1 controls N-glycosylation of E-cadherin, the major epithelial cell–cell adhesion receptor and a tumor suppressor, thereby affecting intercellular adhesion and cytoskeletal dynamics." (PMID 24742667, 2014). "Indeed, other studies using more reliable peptide-MHC tetramer staining have reported higher frequencies tumour-specific T cells in the MC38 model, with Dpagt1-specific CD8+ T cells composing over 20% of CD8+ TILs in D13 tumours." (PMID 37153625, 2023). "In our analyses, NFAT5 and DPAGT1 protein expression was upregulated in the cells of the xenografts under a hyperosmotic cancer microenvironment, and contributed to the enhancement of the progression and invasion of cancer cells of the tumor mass formed by transplanted HSC-3 cells." (PMID 32901097, 2021). "Thus, tumor cells may upregulate DPAGT1 expression by increasing substrate levels and/or by increasing transcriptional regulation as a consequence of activated oncogenic factors, such as HIF1." (PMID 24742667, 2014). "Overall, these results demonstrate that hyperosmotic stress contributed to the activation of DPAGT1 and the subcellular translocation of EGFR via NFAT5 induction in the tumor microenvironment." (PMID 32901097, 2021). "Considering that TM-V exhibits only moderate DPAGT1 inhibitory activity, the tumor regressions reported in TM-V–treated models are unlikely to be explained solely by DPAGT1 inhibition but may instead reflect a combination of partial target engagement and off-target cytotoxic mechanisms." (PMID 41157066, 2025).
cancer (7 papers, 2014 to 2025). A tumor composed of atypical neoplastic, often pleomorphic cells that invade other tissues. "In this study, we found that NFAT5 was upregulated in OSCC cancer cells in association with the upregulation of DPAGT1." (PMID 32901097, 2021). "DPAGT1 encodes the first and rate-limiting enzyme in the assembly of the lipid-linked oligosaccharide precursor in the endoplasmic reticulum and thus mediates N-glycosylation of many cancer-related proteins." (PMID 24742667, 2014). "The therapeutic possibilities of targeting N-glycan biosynthesis with safe and selective DPAGT1 inhibitors are vast, offering countless opportunities to explore novel strategies in cancer treatment." (PMID 41157066, 2025). "This review underscores the emergence of DPAGT1 as a novel and tractable anticancer target, outlining milestones in the discovery of selective inhibitors and their potential to transform cancer therapy." (PMID 41157066, 2025). "In reference to TM-V, MA1 was evaluated for its DPAGT1 enzyme inhibitory activity, antifungal activity, and cytotoxicity against both cancer and normal (healthy) cells." (PMID 41157066, 2025). "Its distinct mechanisms of inducing cell death overturn the prevailing notion that DPAGT1 is an undruggable target in cancer therapy." (PMID 41157066, 2025). "Together, these findings support the clinical potential of DPAGT1 inhibitors as a new class of targeted therapeutics, both as monotherapy and in rational drug combinations for refractory cancers." (PMID 41157066, 2025). "Discovery of alternative natural products or small molecules that have a strong DPAGT1 inhibitory activity with a wide therapeutic window will accelerate the study of the unfolded protein responses in cancers." (PMID 41157066, 2025). "It exhibits sub-100 nM IC50 values against both MraY and DPAGT1 and has demonstrated efficacy against DPAGT1-dependent cancers, making it an excellent starting point for next-generation small molecules." (PMID 41446129, 2025). "EGFR and DPAGT1 were expressed on the cancer cell surface (arrowheads in d and merge e) and in the perinuclear area (arrowheads in g and merge h), respectively." (PMID 32901097, 2021). "Evidence suggests that the connections between DPAGT1 and canonical Wnt signaling are important for cancer development and progression." (PMID 24742667, 2014). "Consistent with a fundamental role in cancer, overexpression of DPAGT1 occurs in cancer cell lines derived from a multitude of tumors from different oral sites." (PMID 24742667, 2014). "In this work, we focus on the application of safer DPAGT1 inhibitors for cancer therapy." (PMID 41157066, 2025). "In addition, The Cancer Genome Atlas (TCGA) data analysis showed a universal increase of DPAGT1 expression in diverse HER2-overexpressing human cancers." (PMID 37463446, 2023). "Given the large increases of N-glycosylation in cancers, along with the impact that dysregulated N-glycosylation can have on a range of signaling processes, targeting DPAGT1 or other N-glycosylation pathway regulators represents a potential approach for cancer treatment." (PMID 24742667, 2014). "Thus, it is likely that altered DPAGT1 expression is an important mechanism by which N-glycosylation is dysregulated in cancer." (PMID 24742667, 2014). "Therefore, besides its overexpression in cancer, heterogeneity in the subcellular location of DPAGT1 protein might also contribute to the acquisition of drug resistance." (PMID 37463446, 2023). "Thus, it is tempting to speculate that dysregulation of DPAGT1/canonical Wnt feedback loop may have an important role in directing “stem cell-like” properties in cancers." (PMID 24742667, 2014). "By selectively targeting DPAGT1, MA1 has the potential to become the first-in-class therapeutic inhibitor of this enzyme, thereby impairing N-glycan biosynthesis in cancer cells while minimizing adverse effects on normal tissues." (PMID 41157066, 2025).
cancer (continued). "Previous studies reported that DPAGT1 gene and proteins were highly expressed in OSCC, and regulated cancer cell proliferation." (PMID 32901097, 2021). "MA1, unlike the promiscuously cytotoxic TM-V, is a stronger DPAGT1 inhibitor that selectively targets cancer cells without harming healthy cells at concentrations higher than 35 μM." (PMID 41157066, 2025).
infection (1 paper, 2024). The state of being infected such as from the introduction of a foreign agent such as serum, vaccine, antigenic substance or organism. "Infection of these gRNA-expressing A549-AC lines with SARS-CoV-2 at various MOI conditions produced consistent phenotypes: (i) knocking out pro-viral ATP6V0D1 or DPAGT1 increased cell viability and (ii) knocking out anti-viral DAZAP2, VTA1, or KLF5 decreased cell viability." (PMID 38168026, 2024).
neurodevelopmental disorder (1 paper, 2021). A behavioral and cognitive disorder with onset during the developmental period that involves impaired or aberrant development of intellectual, motor, or social functions. "In the case of CDG with the primary neurological phenotype (neurodevelopmental disorders), including ALG1-CDG, ALG3-CDG, ALG13-CDG, and DPAGT1-CDG, liver is affected in a minority of patients." (PMID 34291020, 2021).
DPAGT1 also shares sentences with these, for which no sentence is quoted: Hypertension (5 papers); microcephaly (3); myopathy (3); diabetes (2); disorder of glycosylation (2); epilepsy (2); Intellectual disability (2); myasthenia (2); type 2 diabetes (2); Alpers syndrome (1); bipolar disorder (1); cardiovascular disease (1); channelopathies (1); chronic kidney disease (1); colorectal cancer (1); congenital cataracts (1); COVID-19 (1); cutis laxa (1); depression (1); diabetic kidney disease (1); dilated cardiomyopathy (1); epileptic encephalopathies (1); fructose intolerance (1); gastric cancer (1); hearing loss (1); Hyperglycemia (1); infantile spasms (1); kidney damage (1); Leigh syndrome (1); liver disease (1).
A further 6 diseases each share a sentence with DPAGT1 in 1 paper.